CCR6 (C-C motif chemokine receptor 6)
Diseases named in the same sentence as CCR6 in open-access papers (continued):
Sharing a sentence is not in itself a finding about the gene and the disease.
multiple sclerosis (19 papers, 2008 to 2025). A progressive autoimmune disorder affecting the central nervous system resulting in demyelination. "It is associated with increased disease activity in multiple sclerosis together with an increase in CCR6+CD4+ T cells with migratory properties." (PMID 35378908, 2022). "To determine whether α-syn vaccination had modified the capability of T cells to migrate to the brain, we measured the expression of CCR6, a chemokine receptor implicated in T cell brain homing in the animal model of multiple sclerosis (EAE)." (PMID 27055651, 2016). "CCL20 is an inflammatory chemokine, which is upregulated during inflammation to recruit primarily CCR6-expressing leukocytes, with a well-established role in diseases such as multiple sclerosis or its animal model experimental autoimmune encephalomyelitis." (PMID 37554323, 2023). "Considerable attention has been given to CCR6+ IL-17-secreting CD4+ T cells (Th17) in the pathology of a number of autoimmune diseases including multiple sclerosis (MS)." (PMID 28336414, 2017). "Furthermore, depletion of CCR6+ Th cells from donor leukocytes prevents recipients from severe disease in experimental autoimmune encephalomyelitis, a model for multiple sclerosis in mice." (PMID 18698357, 2008). "Therefore, CCR6 blocks could have potential therapeutic use in multiple sclerosis." (PMID 37092451, 2023). "The choroid plexus (ChP) has been suggested as an alternative central nervous system (CNS) entry site for CCR6+ Th17 cells during the initiation of experimental autoimmune encephalomyelitis (EAE), an animal model for multiple sclerosis (MS)." (PMID 37264368, 2023). "A significant up-regulation of CCR6 expression has been observed in Treg cells in the central nervous system (CNS), blood, spleen and lymph nodes cells in mice with experimental autoimmune encephalomyelitis (EAE), a mouse model of multiple sclerosis." (PMID 37092451, 2023).
lung carcinoma (18 papers, 2011 to 2024). "On the other hand, CCR6+ILC3s (Lti cells) have an anti-tumoral role in chemotherapy treated lung cancer by secreting CXCL10, which is a chemoattractant of CD4+ and CD8+ T cells." (PMID 36341381, 2022). "Lung cancer-derived exosomes inhibit the migration of DCs to lymph nodes by broadly decreasing the C-C/C-X-C chemokine receptors, especially CCR6, CCR7, and CXCR3, on DCs." (PMID 34572829, 2021). "Using the sc-RNAseq datasets, we found that the CCR6 was highly expressed in both B cells and a sub-cluster of T cells in both blood and lung cancer tissues." (PMID 35069521, 2021). "Adrenal glands have a high expression of the chemokine CCL20, whereas lung cancer cells frequently express its ligand CCR6, possibly explaining the frequency of adrenal metastases from lung cancer." (PMID 30328287, 2018). "A previous study demonstrated that CCL20/CCR6 are involved in the metastasis of a variety of tumors, including prostate, colorectal and lung cancer." (PMID 29788995, 2018). "It was found that patients developed the adrenal metastasis after resections of primary NSCLC and had high levels of CCL20 in adrenal glands responsible for the selective recruitment of CCR6‐expressing cancer cells from the lung cancer." (PMID 26968871, 2016). "To test the potential pro-carcinogenic effects of CCL20 and CCR6 in lung cancer, we first aimed to characterize the expression and tissue localization of this chemokine/chemokine receptor pair in NSCLC tumors." (PMID 21949768, 2011). "It was revealed the chemokine CCL20, which specifically bind to CCR6 plays a significant role in development of NSCLC by regulation of lung cancer cell proliferation, apoptosis, migration, EMT, as well as they are involving in modification of the immune response to cancer." (PMID 37316552, 2023). "Also in our study was proved a change in the expression of CCL20 and CCR6 mRNA in lung cancer tissue." (PMID 37316552, 2023). "The increased production of CCL20 from adrenal glands might contribute to the selective recruitment of CCR6‐expressing cancer cells in lung cancer 12, although the mechanism by which CCL20 is involved in the formation of lung cancer remains unclear." (PMID 26968871, 2016). "The increase of metastatic potential of CCR6-expressing lung cancer cells may result from a decrease in local production of CCL20 by the tumor cells themselves (and possibly also by stromal cells), which facilitates migration of tumor cells away from their original site." (PMID 37316552, 2023). "Immunohistochemistry revealed CCR6 expression in human lung tissue from patients suffering from fibrotic lung diseases but not in tissue from lung cancer patients." (PMID 38334630, 2024). "Furthermore, regarding the anti-tumoral role of CCR6+ILC3s, experiments with murine TC-1 transplantable lung cancer model demonstrated that CCL20 and IL-1β induce the CCR6+ILC3s recruitment and activation to the tumor." (PMID 36341381, 2022). "In the lung carcinoma syngeneic model, we confirmed that RORγt agonist treatment increased intratumoral CD8+ T cells and MoDCs through the promotion of CXCL10 as well as promotion of Type 17 T cell migration via upregulation of CCL20 and CCR6 expression." (PMID 35459193, 2022). "In addition, a recent study also identified that CCL19, CCL20, and CXCL13 are highly expressed in lung cancer, and subsequent co-expression of CCL20 receptor CCR6 in CAR-T increased cell migration and tumor killing." (PMID 34553036, 2021). "A higher CCR6 and CCL20 mRNA expression level was observed in the AC group compared to the SCC group, which may be responsible for stronger biological aggressiveness of this histopathological type of lung cancer." (PMID 37316552, 2023).
experimental autoimmune encephalomyelitis (17 papers, 2008 to 2024). An autoimmune demyelinating disease of the central nervous system that is produced experimentally in animals by the injection of homogenized brain or spinal cord in Freund's adjuvant. "Here we identify a temporally regulated IL-23-dependent switch from CCR6 to CCR2 usage by developing Th17 cells that is critical for pathogenic Th17 cell-driven inflammation in experimental autoimmune encephalomyelitis (EAE)." (PMID 26511769, 2015). "Reduced Treg migration was also observed in the central nervous systems of the experimental autoimmune encephalomyelitis model Rag1 knockout mice reconstituted with bone marrow of CCR6 knockout mice." (PMID 32240221, 2020). "Fox example, CCR6 is essential for the optimal recruitment of Th17 cells to sites of Th17-mediated inflammation in experimental autoimmune encephalomyelitis (EAE)." (PMID 25768730, 2015). "Fox example, CCR6 is essential for the optimal recruitment of Tregs to sites of Th17-mediated inflammation in experimental autoimmune encephalomyelitis (EAE)." (PMID 21935436, 2011). "Studies using experimental autoimmune encephalomyelitis (EAE) models have shown that the T cell infiltration into the CNS is reduced in CCR6-null mice, suggesting that Th17 cells lacking CCR6 cannot effectively invade the CNS." (PMID 39857624, 2024). "Lack of CCR6 in Th17 cells reduces the severity of experimental autoimmune encephalomyelitis and Th17 and Treg recruitment into inflammatory tissues." (PMID 25691899, 2015). "The functionality of CCR6+ Th17 cells was demonstrated in adoptively transferred experimental autoimmune encephalomyelitis (at-EAE); transfer of lymph node cells containing CCR6+ Th17 cells led to severe disease while depletion of CCR6+ Th cells attenuated the course of at-EAE." (PMID 18698357, 2008). "Experimental autoimmune encephalomyelitis (EAE), a rodent model sharing features with MS, revealed not only that the pro-inflammatory CCR6-directed Th17 cells enter the CNS via the choroid plexus, a distinct meningeal structure, but also are involved in eLF induction." (PMID 32010141, 2019).
Autoimmunity (15 papers, 2015 to 2025). The occurrence of an immune reaction against the organism's own cells or tissues. "CCR6, the gene encoding chemokine (C-C motif) receptor 6, a surface marker for Th17 cells at 6q27, is critically involved in IL-17A-driven autoimmunity in diseases and associated with RA susceptibility." (PMID 27822475, 2016). "The CD27 and CD70 costimulatory pathway has been found to inhibit the transcription of the key effector molecules IL-17 and the chemokine receptor CCR6, subsequently attenuates associated autoimmunity, Cancer cells can reprogramme their metabolism to support cell growth and proliferation." (PMID 37732314, 2023). "Taking this into consideration, our results may suggest that reducing the availability of glutamine to the CD4+ cells might have beneficial effect on reducing T cells promoting autoimmunity by decreasing pathogenic CCR6 and CXCR3 bearing T cell and increasing regulatory T cells." (PMID 27467144, 2016). "During inflammation, increased CCL20 expression drives the recruitment of CCR6+ immune cells to regulate the immune response, inflammatory response, autoimmunity, and alloimmunity." (PMID 36118358, 2022). "We also analyzed Th1/17 (CCR6+CXCR3+) cells which were originally related to autoimmunity, but recently turned out to be significant in microorganism infections including dengue virus." (PMID 33072068, 2020). "Further, Th17 cells expressing CXCR3+CCR6+ are associated with protection against Mtb, while those displaying CCR6+ CCR4+ are involved in autoimmunity." (PMID 28985739, 2017). "In models of autoimmunity, cancer and infection, activation-induced downregulation of CCR6 releases γδT17 cells from their homeostatic immunosurveillance trafficking circuit through the skin and circulation, which then enhances their CCR2-dependent homing to inflamed tissue." (PMID 28580944, 2017). "Recent literature suggests that certain pathogenic Th17 cell subsets with Th1 characteristics, such as CD4+CD161+CCR6+CXCR3+IL-17+IFN-y+ (Th17.1) and CD4+CD161+CCR6+CXCR3+IL-17-IFN-y+ (exTh17), are important contributors in Th1-mediated autoimmunity." (PMID 35967358, 2022). "While CCR6 recruits resting γδT17 cells to the dermis, CCR2 drives rapid γδT17 cell recruitment to inflamed tissues during autoimmunity, cancer and infection." (PMID 28580944, 2017). "The existence of functionally distinct IL-17A-producing CD4+ T-cells cells was originally reported in the context of autoimmunity, with CCR6+CXCR3+Th1Th17 and CCR6+CCR4+Th17 cells being considered pathogenic and non-pathogenic, respectively." (PMID 27553844, 2016). "CXCR3− CCR6+ cTfh cells in IRs may suggest their role in autoimmunity, rather than CD4+ recovery." (PMID 40130906, 2025).
HIV-1 infection (15 papers, 2015 to 2025). The type species of lentivirus and the etiologic agent of acquired immunodeficiency syndrome (AIDS). "Immature DCs express CCR6 and are susceptible to HIV-1 infection, and our lab has demonstrated this in our NHP studies." (PMID 41191579, 2025). "As CD161+ CD4+ T cells are memory cells, expressing high levels of CCR5, CCR6, and integrin α4, a phenotype associated with susceptibility to HIV-1 infection, we studied how these cells are affected during untreated AHI." (PMID 33322496, 2020). "Altogether, these results point out that Th17 and CCR6+DN, two major populations that are susceptible to HIV-1 infection, are enriched in SAMHD1low cells from infected patients." (PMID 31220191, 2019). "Additionally, there is an observed increase in T cell populations expressing surface markers associated with gut-homing (CD161 and CCR6) as well as susceptibility to HIV-1 infection (CCR5 and β7 integrin)." (PMID 38389539, 2024). "The gut associated lymphoid tissue (GALT) is enriched in CCR6+CD4+ T cells including Th17 cells which are preferentially depleted in HIV-1 infection and pathogenic simian immunodeficiency virus (SIV) infection of rhesus macaques, starting during acute infection." (PMID 28509877, 2017). "Since these cells are not restored in the GALT during ART, it can be postulated that the CD4+CCR6+ cell population is a major target for HIV-1 infection that in PLWH contributes to the inflammatory environment in both GALT and peripheral blood." (PMID 35418589, 2022). "A meta-analysis using the NCBI HIV-1 interactions database allowed theidentification of human genes previously involved in HIV-1 infection that aremodulated by T0070907 in CCR6+ T cells." (PMID 33089034, 2020). "Similar reports are found in HIV-1 infection, whereby continuous stimulation of immune system impairs the migration ability of circulatory CCR6+ CXCR3+ Th cells from blood to peripheral organs." (PMID 31635276, 2019). "In this manuscript we used a systems biology approach to characterize the heterogeneity of memory subsets expressing the Th17 marker CCR6 at homeostasis and during HIV-1 infection." (PMID 27553844, 2016). "The CCL20/CCR6 axis has earlier been discussed in the context of HIV-1 infection." (PMID 33659876, 2021). "Thus, CCL20/CCR6 is considered to be a “double-edged sword” concerning HIV-1 infection (Lee and Körner, 2017)." (PMID 33659876, 2021). "A model suggested to explain this apparently paradoxical result was that high CN may promote increased recruitment of CCR6 expressing cell types that are highly permissive for HIV-1 infection thus amplifying the foci of HIV-1 infection." (PMID 25852686, 2015). "Furthermore, the proportion of CCR6+ Th17 cells, reported to be highly permissive for HIV-1 infection was significantly enhanced in elderly individuals." (PMID 26452480, 2015). "Thus, reducing CCR6+ T cells might be a consequence of HIV-1 infection, also happening in EC." (PMID 33659876, 2021). "CCR6+ CD4+ T cells are highly permissive to HIV-1 infection, and are depleted from peripheral blood during chronic HIV-1 infection (CHI)." (PMID 33322496, 2020). "CCR6 is expressed on DCs and memory CD4+ and CD8+ T cells, indicating a potentially important role for HBD2 in preventing HIV-1 infection in CCR6+ target cells through the upregulation of additional innate antiviral factors." (PMID 28839349, 2017). "It has been shown that CCR6+CCR4+, CCR6+CXCR3+ and CCR6+CD90+ Th17 cell subsets are highly permissive to HIV-1 infection." (PMID 28509877, 2017). "Finally, CCR6 levels were reduced on MAIT cells in HIV-1 infection, but not on iNKT cells." (PMID 29971068, 2018).
influenza (14 papers, 2014 to 2025). An acute viral infection of the respiratory tract, occurring in isolated cases, in epidemics, or in pandemics; it is caused by serologically different strains of viruses (influenzaviruses) designated A, B, and C, has a 3-day incubation period, and usually lasts for 3 to 10 days. "CCR6+ γδ T cells have been implicated in lung tissue repair in influenza-infected neonates and in protecting the liver from excessive inflammation and fibrosis in the murine model of chronic liver injury." (PMID 36526890, 2022). "We found little expression of both CD25 and CCR6 on the influenza-specific as well as the general CD4 population, while such phenotypes were detected in α-enolase- and CILP/fibrinogen-specific T cells." (PMID 32423478, 2020). "This difference in mRNA was also reflected at the protein level, with the proportion of CXCR3+ cTfh cells increasing after influenza vaccination and a reciprocal decrease in CCR6+ cTfh cells." (PMID 31175140, 2019). "Activation of CXCR3+ CCR6- cTFH is observed in response to both novel and recall antigenic challenges, as suggested by their activation after both influenza vaccine and HBV." (PMID 30303980, 2018). "It has been reported that the frequency of CXCR3+ Tfh1-like cells increased, while it decreased for CCR6+ Tfh17-like cells at D7 post-influenza vaccination." (PMID 26333070, 2015). "Examination of CCR6 expression on vaccine-primed Th17 cells demonstrated a heterogenous profile 5 days after influenza challenge with approximately 50% IL-17A+ CD4+ T cells lacking the chemokine receptor." (PMID 24465206, 2014). "Likewise, infection with either SARS-CoV-2 or influenza, led to an expansion of CCR6+CXCR3− bystander memory B cells (MBCs) alongside the CCR6+CXCR3+ virus-specific MBCs in the lungs of the infected animals." (PMID 41149075, 2025). "In general, CXCR5, compared to CXCR3 and CCR6, is the chemokine receptor that was most prominently expressed on tetramer-positive cells with mean levels of up to 40% for citrulline-specific and 54% for influenza-specific populations while for the general CD4+ population it was only around 10%." (PMID 32423478, 2020). "Overall, dynamics of the three cTFH cell subpopulations (cTFH1 [CD3+CD4+CXCR5+CXCR3+CCR6−], cTFH2 [CD3+CD4+CXCR5+CXCR3−CCR6−], and cTFH17 [CD3+CD4+CXCR5+CXCR3−CCR6+]) differed after influenza vaccination." (PMID 36705404, 2023). "In the influenza compartment, we observed an increased signal for Th1 (CXCR3+CCR6−) cells." (PMID 39557489, 2024). "Lastly, CCR6-expressing T cells were found to be rare, also amongst the influenza-reactive T cells and virtually absent amongst citrulline-specific T cells in the patients responding to treatment at the 6 months follow-up." (PMID 32423478, 2020). "Similarly, we examined the surface expression of the chemokine receptors CCR6, CXCR3 and CXCR5 and found a general decrease in the frequency of CXCR5+ cells for all autoreactive as well as the influenza-specific T cells at follow-up." (PMID 32423478, 2020). "cTFH that express CXCR3 but not CCR6 transiently increase 7 days following influenza vaccination, are antigen-specific, upregulate expression of ICOS and PD-1, and correlate with both serological response and the day 7 peak in PB." (PMID 30303980, 2018). "Interestingly, we observed that seasonal influenza vaccination elicited median increases in PD-1 MFI on both CCR7- and CCR7+ subsets, specifically in CXCR3+CCR6- cTFH, and the magnitude of increase was greater within the CCR7- subset." (PMID 30303980, 2018). "Extensive surface phenotyping was performed together with combinatorial tetramer staining to measure the frequency, memory status (CD45RA and CCR7), chemokine receptor expression (CXCR3, CCR4, CCR6 and CXCR5) as well as activation status (CD38) of these influenza-specific T cells." (PMID 27571776, 2016).
influenza (continued). "However, in contrast to our results, in the influenza–tracheal infection model, depletion of the IL-17A–producing Vγ4+CCR6+ γδ T-cell subset did not affect accumulation of NK cells." (PMID 39504049, 2024). "Alternatively, this decrease in CCR6+ c-Kithi ILC2 levels could also be due to migration of these cells to lung, where ILC2s have been shown to play an important role in tissue repair during influenza infection in mice." (PMID 39038044, 2024). "Of note, among influenza- and citrulline-specific cells as well as in the general CD4 population around half of the CXCR3+ cells also expressed CXCR5 and to a lesser extent CCR6 (data not shown)." (PMID 32423478, 2020). "In contrast to this we found only a few influenza-specific cells co-expressing several chemokine receptors, these were mostly CXCR3+ cells carrying CCR6 and/or CXCR5 (data not shown)." (PMID 32423478, 2020). "In contrast to what was observed in the UK unadjuvanted influenza vaccination cohort, there was no significant change in the CXCR3 or CCR6 transcripts, indicating that the Th1/2/17 phenotype of these cTfh cells is not skewed by either adjuvant." (PMID 31175140, 2019).